POLD1 (DNA polymerase delta 1, catalytic subunit)
Diseases named in the same sentence as POLD1 in open-access papers (continued):
Sharing a sentence is not in itself a finding about the gene and the disease.
cancer (continued). "Exome-sequencing results based on the TCGA analysis indicated the specific association of POLD1 mutations with hyper-mutated cancers." (PMID 33442399, 2021). "Somatically acquired heterozygous missense mutations in the POLE or POLD1 exonuclease domains found in some human cancers cause defective proofreading and, consequently, high burdens of somatic mutations with distinctive mutational signatures." (PMID 34594041, 2021). "A pan-cancer analysis of POLE/POLD1 mutations in 47,721 patients showed that 185/2586 esophagogastric cancer patients harbor such mutations." (PMID 33916348, 2021). "High expression levels of POLD1 were found to be closely associated with tumor purity, immune scores and stromal scores in pan-cancers." (PMID 34868924, 2021). "Patients with POLE/POLD1 mutations exhibited a significantly preferable prognosis in a multi-cancer-ICI cohort with 1644 patients." (PMID 34747716, 2021). "The assessment of the functional impact of cancer-associated DNA polymerase δ and ε variants (POLD1 and POLE) has been evaluated in yeast by constructing strains carrying the correspondent mutated amino acid identified by aligning yeast and human sequences." (PMID 32656256, 2020). "Mutation-driven genomic instability occurs in POLE- or POLD1-mutated cancers, where the levels of mutational burden (based on SNVs) in POLE exonuclease domain mutated cancers are extremely high." (PMID 31747945, 2019). "Thirdly, in this study, patients with POLE or POLD1 damaging mutations had a significantly higher incidence of cancer than those with POLE&POLD1 WT in age groups less than 40, 50 or 60 years old." (PMID 31673068, 2019). "There are some case reports showing that cancer patients with POLE or POLD1 damaging variants can benefit from immunotherapy." (PMID 31673068, 2019). "Few alternation of A→G mutation frequency in cancers with only POLD1 or only POLE mutations can be explained by the strong function complementarity between POLD1 and POLE, reducing the influence of error-prone DNA polymerases." (PMID 28582771, 2017). "POLE/POLD1-mutated cancers displayed high SBS rates, ranging from 227 to 14,695 exonic events, compared to a range of 22 to 2,014 in cancers lacking POLE/POLD1 mutations." (PMID 24705290, 2014). "The somatic mutation spectrum of POLE and POLD1 in the common cancers will be increasingly well described in the coming months as further large-scale sequencing programmes come to fruition." (PMID 23447401, 2013). "A particularly interesting issue is why germline POLE or POLD1 mutations can cause cancer, yet only POLE is somatically mutated." (PMID 23447401, 2013). "However, when this proofreading function is compromised by mutations in POLD1, particularly in its exonuclease domain, Pol δ contributes to genomic instability—a hallmark of cancer." (PMID 40661943, 2025). "Signatures hypothesised to increase in activity include SBS20 (POLD1 mutations) in both cancer types in which it is active, and SBS31 (platinum chemotherapy)." (PMID 39966709, 2025). "The accumulation of such structural variations represents a distinct dimension of POLD1-driven genomic instability, complementing the hypermutation phenotype and contributing to the overall genomic instability characteristic of POLD1-mutated cancers." (PMID 40661943, 2025). "However, POLD1 mutations—particularly in this domain—disrupt this function, triggering genomic instability and a hypermutated state in cancers." (PMID 40661943, 2025). "There is also a distinct pathogenic mechanism in POLD1 where the polymerase activity is lost, associated with an extremely rare constitutional disorder unrelated to cancer predisposition: Mandibular hypoplasia, Deafness, Progeroid features, and Lipodystrophy (MDPL) syndrome (OMIM: 615381)." (PMID 41487566, 2025).
cancer (continued). "Finally, we integrate structural biology, tumor evolution, and clinical oncology insights to argue that POLD1’s dual role as a mutator and immunogenic trigger offers a new paradigm for precision cancer therapy." (PMID 40661943, 2025). "Generally, there are much less cancer driver mutations in POLD1 than in POLE in human cancers." (PMID 37891003, 2024). "We could expect somatic MMR inactivation as an alternative mechanism; however, dMMR is rarely found in cancers from individuals with constitutional heterozygous POLD1 mutations." (PMID 38658779, 2024). "Nonetheless, somatic mutations of the POLD1 gene are inadequately studied in cancer." (PMID 36980791, 2023). "Previous studies have shown that POLD1 is associated with the progression of various cancers." (PMID 37047824, 2023). "Moreover, patients with cancers generating POLD1-mutation-related SBS signatures demonstrated an enhanced response to ICI treatment." (PMID 36980791, 2023). "Here we present specific recommendations to apply the ACMG/AMP guidelines for the classification of variants located in the ED of POLE and POLD1, -where the variants associated with cancer predisposition are found-, and the scientific rationale applied for their definition." (PMID 37848928, 2023). "Although cancers harboring POLD1 mutation are believed to be primarily microsatellite stable, some of them may display an MSI-H phenotype." (PMID 36980791, 2023). "In addition, the proofreading defect caused by inactivating mutations in the POLD1 proofreading (exonuclease) domain leads to a significant increase in somatic mutation load and cancer risk." (PMID 37047824, 2023). "Therefore, our aim is to summarize and update the current understanding of the POLD1 mutations and expression changes in human cancers." (PMID 36980791, 2023). "Furthermore, recent studies have also indicated that POLD1 proofreading domain mutation can potentially predict the clinical benefit in cancer patients who are treated with immune-checkpoint inhibitors (ICIs)." (PMID 37047824, 2023). "In humans, there are far fewer cancer driver mutations in POLD1 than in POLE." (PMID 37388540, 2023). "Moreover, we address possible therapeutic implications and future challenges in POLD1-mutated cancers." (PMID 36980791, 2023). "Although POLD1 mutations in cancers seem to be understudied, they may serve as promising prognostic/predictive biomarkers in the future and, importantly, future targets for novel POLD1-oriented therapies." (PMID 36980791, 2023). "Surprisingly, one recent study on Chinese genomic cancer population data suggests that EC may be the most common malignancy with POLD1 mutations among all cancers." (PMID 36980791, 2023). "Besides cancer, some other diseases occur due to the mutation in POLD1 gene, that is, Mandibular Hypoplasia, Deafness, Progeroid Features, and Lipodystrophy Syndrome." (PMID 35620275, 2022). "Carriers of POLE and POLD1 exonuclease domain germline mutations exhibited elevated somatic mutation burdens without evident cellular or organismal consequences, other than an increased cancer risk." (PMID 35803914, 2022). "The hypermutated condition may be related to driver mutations in the DNA polymerase ε (POLE) and δ1 (POLD1) genes among different tumor types, including colorectal, endometrial, and other cancers such as melanoma and lung cancer." (PMID 34026645, 2021). "Germline POLE/POLD1 mutations cause familial cancer predisposition." (PMID 34594041, 2021). "However, when present, POLE/POLD1-mutated cancers are associated with a high tumour mutational burden; hence, their use has also been suggested in predicting efficacy of immunotherapy." (PMID 34694371, 2021). "In addition, several immune cells, including B cells, T cells, dendritic cells, macrophages and neutrophils, were significantly associated with POLD1 expression to varying degrees in different cancers, especially HCC (r2>0.4)." (PMID 34868924, 2021).
cancer (continued). "POLD1 is involved in controlling DNA repair and has been shown to be associated with cancer." (PMID 33519918, 2020). "Immunotherapy provided very encouraging data on survival for MSI-H/dMMR mCRC and might be the best area of research, even for MSS POLE-1 or POLD1 mutant cancers, due to their high mutational burden." (PMID 32413973, 2020). "Interestingly, cancers only developed in mice homozygous for proofreading deficient polD1 and polE alleles and in mismatch proficient background." (PMID 29500597, 2018). "We first analyze the molecular mechanisms by which domain-specific POLD1 mutations—whether in the exonuclease, polymerase, or regulatory regions—drive genomic instability and fuel cancer progression across diverse clinical contexts, from PPAP to sporadic malignancies." (PMID 40661943, 2025). "Analysis using databases like TIMER has revealed that POLD1 expression, and by extension mutations, correlates with increased infiltration of immunosuppressive cells, such as regulatory T cells (Tregs) and myeloid-derived suppressor cells (MDSCs), in cancers like ccRCC." (PMID 40661943, 2025). "In this scenario, mutation of POLD1 gene, which has a DNA-proofreading function, is strongly correlated with high mutation load and neo-antigen generation, thus representing a potential marker for predicting the efficacy of IC inhibitor therapy in different types of cancer, including SS." (PMID 40918137, 2025). "In addition, germline mutations in CHEK2 have been found with a prevalence of 4% in patients with PanC, and a number of genetic alterations of the proofreading domain of DNA polymerases, such as POLE or POLD1, have been associated with the risk for human cancers." (PMID 36717774, 2023). "Whereas an overwhelming number of studies in the last decades have focused on POLD1 pathogenic variants in a wide range of neoplasms, only a few studies have validated the prognostic and predictive utility of POLD1 mRNA and protein expression in human cancers to date." (PMID 36980791, 2023). "Furthermore, the tumor phenotypes and POLE/POLD1 expression levels correlate with tumor mutation burden and tumor driver gene expression according to an analysis of a panel of mutations in 1,392 Chinese patients with cancer." (PMID 34950188, 2021). "Genetic instability such as MSI, POLE, and POLD1 defects lead to an increased mutation burden which arises as a leading biomarker of response to immune blockade inhibitors, new drugs that have improved outcomes in several cancer types through immune stimulation." (PMID 30275357, 2018). "However, similar exclusion of families carrying APC, MUTYH or POLE and POLD1 mutations because known cancers other than CRC are rare or unknown in these syndrome, and exclusion based on CRC would have defeated the purpose." (PMID 28701784, 2017). "Intriguingly, despite this interaction, most POLD1-mutated tumors maintain MSS, distinguishing them from classical MMR-deficient cancers characterized by microsatellite instability (MSI)." (PMID 40661943, 2025). "Despite its promise, the prognostic and therapeutic significance of POLD1 remains contentious, varying across cancer types." (PMID 40661943, 2025). "For example, the mere 2-3-fold increase in mutation rates increases the cancer risk of patients with MUTYH, and 1.2-7-fold for POLE and POLD1 mutations." (PMID 40243939, 2025). "Current gene- and disease-informed specifications are under development for the MUTYH, POLE and POLD1 genes, and other adenomatous and hamartomatous polyposis genes will follow to optimize clinical management and opportunities for cancer prevention." (PMID 40237887, 2025). "Future studies will focus on characterizing the impact of rare POLE and POLD1 mutations, such as the described POLE E1977* variant, to somatic hypermutation in cancer." (PMID 40575172, 2025).
cancer (continued). "Similar signatures to our result were reported in patients with mutations of POLD1 and MUTYH, defective DNA MMR/BER, and with the habit of tobacco smoking producing reactive oxygen species in COSMIC catalog of somatic mutations in cancer (ver." (PMID 39159810, 2024). "Cancer patients in whom the suspected diagnosis of CMMRD cannot be confirmed should probably be tested for germline POLE and POLD1 exonuclease domain variants (Rec." (PMID 39420201, 2024). "These cancers are often linked to constitutional MMRD and the subsequent acquisition of a somatic POLE/POLD1 mutation, which results in the rapid accumulation of mutations." (PMID 39204096, 2024). "DNA polymerase 1 (POLD1) has an important role in DNA damage repair and is frequently upregulated in cancer." (PMID 37105989, 2023). "We first evaluated POLD1 expression in TCGA pan-cancer according to the TIMER online platform, and found higher POLD1 expression in various human tumors compared with their counterpart normal tissues." (PMID 37047824, 2023). "Recently, POLD1 protein level was shown to be negatively correlated with the expression of cadherin-16 in this cancer." (PMID 36980791, 2023). "However, the exact way that high levels of POLD1 cause cancer is still unknown." (PMID 37105989, 2023). "Nevertheless, the complex regulatory mechanisms of POLD1 expression in cancers remain to be fully characterized." (PMID 36980791, 2023). "In this study, we assessed the impact of the POLD1 p.(Lys648fs*46) variant detected by whole-exome sequencing in a proband with familiar history of SPS and cancer." (PMID 36756361, 2023). "Their analysis demonstrated that among ICI-treated cancer individuals, patients with either POLE or POLD1 mutations have significantly longer overall survival in comparison with those without." (PMID 36980791, 2023). "We prepared EBV-transformed cell lines from the primary lymphocytes of 3 patients bearing candidate variants (henceforth referred to as the POLD1/POLH cell line, POLE cell line, and POLK cell line) and from several age-and gender-matched cancer-free controls." (PMID 37095444, 2023). "Studies concerning uveal melanoma, the most common primary intraocular malignancy in adults, have discussed the changes in POLD1 expression patterns within patients with this cancer." (PMID 36980791, 2023). "Recently, a pan-cancer study showed combining POLE and POLD1 mutation status into a simple model also can efficiently predict response to ICI therapy." (PMID 35344507, 2022). "Several phase 2 clinical trials (such as NCT03461952, NCT02693535, NCT03428802, and NCT03207347) are ongoing to evaluate the efficacy of ICIs or targeted therapies in patients with cancer and POLE/POLD1 mutations." (PMID 35189839, 2022). "Together, these findings strongly suggest that the interplay of this POLD1 variant, likely to impair the proofreading function of POL δ, and the heterozygous PMS2 PV is responsible for the siblings’ AYA colorectal and other cancers." (PMID 36291559, 2022). "In 2019, Wang and his colleagues, through analyzing medical data of 47,721 patients with various cancer types with POLE/POLD1 mutations, proposed that POLE/POLD1 mutations are promising potential predictive biomarkers for positive ICI outcomes." (PMID 36483562, 2022). "We further evaluated the effect of POLD1 mRNA expression on the prognosis of patients with various cancer types." (PMID 35189839, 2022). "Second, to explore the prognostic implications of POLD1 expression in pan-cancers, we performed Cox regression analysis." (PMID 34868924, 2021). "Mutational signatures, tumor mutational burden (TMB), tumor indel burden, and variants in cancer driver genes (BRAF, KRAS, POLE, POLD1 and DNA mismatch repair (MMR) genes) were analyzed for available samples." (PMID 33672345, 2021).
cancer (continued). "POLD1 expression was closely correlated with OS in several cancers, such as PRAD (HR=9.25; P=2.7e-04) and MESO (HR=2.71; P=1.7e-06), and DSS in KIRC (HR=1.93; P=7.4e-04) and ACC (HR=3.48; P=2.6e-06)." (PMID 34868924, 2021). "Based on HCC tissues and adjacent normal tissues from TCGA (n=423) and GTEx (n=533) datasets, we first compared the POLD1 expression level between pan-cancers and normal tissues." (PMID 34868924, 2021). "summarized the POLE/POLD1 mutation rate in 47,721 patients with different cancer types and identified that patients harboring POLE/POLD1 mutations have a significantly higher TMB." (PMID 34026601, 2021). "A recent study investigated 47,721 patients with multiple cancer types and demonstrated a potential predictive role of POLE/POLD1 mutations in beneficial outcomes for ICIs." (PMID 34026622, 2021). "As the FDA has approved pembrolizumab for MSI in various cancer types, it would certainly be interesting to further explore the underlying relationship between POLE/POLD1 mutations with MSI." (PMID 34026622, 2021). "According to the network, POLD1 was observed to interact with ATM, which is a DNA damage response gene commonly mutated in cancer." (PMID 33747905, 2021). "The POLD1 gene has been found silenced in several cancer types—mostly, in conjunction with a defective POLE gene—with increased genome instability and DNA damage effects." (PMID 34026645, 2021). "POLE/POLD1 mutations remained an independent risk factor for greater response to immune checkpoint inhibitor after adjusting for MSI status and cancer type." (PMID 33916348, 2021). "retrieved the genomic data of 21,074 Chinese patients with different cancer types and revealed the predictive value of POLE/POLD1 mutations, especially those in the proofreading domain, in positive outcomes for ICIs." (PMID 34026622, 2021). "The mutational prevalence of POLE is reported to be 2.79%, while that of POLD1 is 1.37% across various cancer types." (PMID 34026622, 2021). "Second, we investigated the prognostic implication of elevated POLD1 expression in HCC and pan-cancers, revealing that increased POLD1 levels were correlated to worse prognoses for HCC patients." (PMID 34868924, 2021). "FANCA was overexpressed in six databases other than LU, and POLD1 was highly expressed in in cancer tissues in six databases other than HENDRIX." (PMID 32762026, 2020). "Two DDR-related genes (POLE and POLD1) were also shown to correlate well with WES-TMB in pan-cancer types." (PMID 32843031, 2020). "Despite multiple targeting rounds, we were not able to establish a homozygous POLD1-/- clone, indicating POLD1 to be an essential gene in cancer cells." (PMID 33144657, 2020). "Identifying error-prone variants of POLD1 and POLE and understanding the mechanisms that underlie their fidelity defects is, hence, also important in the context of cancer therapy." (PMID 31278166, 2019). "Our study clarified the relationship between POLE/POLD1 mutations and MSI and TMB in Chinese cancer patients." (PMID 31673068, 2019). "Our study provided a theoretical and practical basis for patient selection for immunotherapy in Chinese cancer patients with POLE and POLD1 variants." (PMID 31673068, 2019). "1,392 Chinese cancer patients were recruited, and the correlation of POLE/POLD1 variants with existing immunotherapeutic markers and cancer pathways was investigated." (PMID 31673068, 2019). "This suggests that the POLE/POLD1 proofreading defect was present in all cancer cells, and therefore, present in the same cells as the MMR deficiency." (PMID 29717118, 2018). "An alternative cause of hypermutation in cancer is mutations in polymerases epsilon (POLE) and delta 1 (POLD1)." (PMID 30275357, 2018).